IDO1 (indoleamine 2,3-dioxygenase 1)
Diseases named in the same sentence as IDO1 in open-access papers (continued):
Sharing a sentence is not in itself a finding about the gene and the disease.
myocardial infarction (7 papers, 2019 to 2025). Gross necrosis of the myocardium, as a result of interruption of the blood supply to the area, as in coronary thrombosis. "Moreover, IDO1 has been implicated in promoting oxidative stress and apoptosis during myocardial infarction and renal ischemia-reperfusion injury." (PMID 40715082, 2025). "In that paper, it was concluded that myocardial infarction disturbs the balance of the IDO1–KYN–AhR axis in cardiac cells and triggers oxidative stress." (PMID 39000041, 2024). "In conclusion, based on this study, it is possible to conclude that myocardial infarction alters the Ido1-Kyn-Ahr axis in heart tissue cells and imbalances it, as well as triggering oxidative stress." (PMID 36879035, 2023). "The level of the metabolite kynurenic acid (Kna) produced by the action of IDO1, can predict death and recurrent myocardial infarction in patients admitted to the hospital because of acute myocardial infarction." (PMID 35402548, 2022). "Myocardial infarction (MI) affects many molecular pathways in heart cells, including the Ido1-KYN-Ahr axis." (PMID 36879035, 2023). "The cellular alterations in myocardial infarction involve a wide range of molecular pathways, including KYN metabolism and the IDO1–KYN–AhR axis." (PMID 39000041, 2024).
ovarian tumor (7 papers, 2015 to 2025). "In line with this, we found that IDO1 inhibition alone (epacadostat), TDO2 inhibition alone (680c91), and dual TDO2/IDO1 inhibition (AT-0174) all reduced PD-L1 expression on ovarian tumor cells." (PMID 38451784, 2024). "In EOC patients, elevated IDO1 expression correlated with a lower Trp:Kyn ratio in the ovarian tumor microenvironment, reduced CD8+ TIL frequency, poor prognosis, and suppression of T cell responses." (PMID 34025677, 2021). "Here we show that tumoral IDO1 expression led to profound changes in tryptophan, nicotinate/nicotinamide, and purine metabolic pathways in the ovarian tumor microenvironment, and to an increased frequency of PD-1+CD8+ tumor infiltrating T cells." (PMID 34025677, 2021). "Dynamic changes in the metabolic profile of intraperitoneal IDO1-expressing ovarian tumors were evaluated by LC-MS measurement of Kyn and its downstream catabolites." (PMID 34025677, 2021). "In that study, 8 of 10 ovarian tumor specimens were positive for IDO1 overexpression." (PMID 40512849, 2025).
pneumonia (7 papers, 2020 to 2024). An acute, acute and chronic, or chronic inflammation focally or diffusely affecting the lung parenchyma, caused by an infection in one or both of the lungs (by bacteria, viruses, fungi, or mycoplasma.). "An intriguing finding in PACS cases of this series was the occurrence of morphological and immunophenotypical changes in the pulmonary vascular bed, similar to those observed in acute early/mild cCOVID-19 pneumonias (vascular enlargement and abnormal endothelial expression of IDO1, PD-L1 and STAT3)." (PMID 35740354, 2022).
pulmonary TB (7 papers, 2019 to 2026). "Elevated IDO-1 activity and higher kynurenine/tryptophan ratios have been associated with an increased mortality in pulmonary TB, suggesting its potential prognostic use." (PMID 41553570, 2026). "In addition, IDO1+ macrophages have been implicated in immunosuppressive functions in the context of lung tuberculosis." (PMID 39399649, 2024). "Previous studies revealed that pulmonary TB patients had significantly higher expression of IDO1 and Kyn concentration in serum compared to healthy individuals." (PMID 36253713, 2022). "Moreover, IDO1‐expressing macrophages, known for their suppressive functions in pulmonary tuberculosis, provide a parallel reference to other respiratory infections like MPP, highlighting the conservation of these suppressive mechanisms across diverse pulmonary conditions." (PMID 39399649, 2024).
type 2 diabetes (7 papers, 2017 to 2023). "We also showed that IDO1 and KAT3 were inversely associated with type 2 diabetes which has rarely been studied previously." (PMID 31186442, 2019). "Unexpectedly, we also found that IDO1 was protective against type 2 diabetes." (PMID 31186442, 2019). "Interestingly, glomerular IDO1 expression was upregulated in a rodent model of type 2 diabetes." (PMID 28612106, 2017).
B cell lymphomas (6 papers, 2014 to 2023). "Interestingly, in a pre-clinical mouse model of B cell lymphomas, Ly6Clow monocytes (corresponding to the ncMO) accumulated and showed high levels of immunosuppressive genes (PD-L1, PD-L2, Arg1, IDO1, and CD163) associated with suppression of T cell proliferation." (PMID 34975843, 2021). "Expression analysis of 215 human mature aggressive B-cell lymphomas revealed a positive correlation of IDO1 with STAT3." (PMID 24657910, 2014). "Expression analysis in human B-cell lymphomas showed a positive correlation between IL-6 and IDO1." (PMID 24657910, 2014). "Furthermore, expression analysis of human B-cell lymphomas revealed a correlation of AHR and AHR target gene expression with IDO1." (PMID 24657910, 2014).
Chlamydia infection (6 papers, 2018 to 2025). "Among the target genes, we found the key antichlamydial gene ido1 which is known to be induced by Chlamydia infection and interferon, especially IFNG." (PMID 34819931, 2021). "The lung IDO2 mRNA was clearly induced by Chlamydia infection, but its RNA-seq read numbers were significantly lower than IDO1 reads." (PMID 31249813, 2019). "Moreover, we also discovered a significant positive correlation between Creb3 and Ido1 expression in GC cells, which is thought to possibly constrain the specific expression of Ido1 in GC cells by inhibiting Creb3 activity post-Chlamydia infection, leading to impaired GC cell barrier function." (PMID 40786607, 2025). "Next, we explored whether the expression of IFN-γ and IFN-γ induced genes was altered in FP- and BUD-treated lung tissues, including the typical, inducible defence genes against Chlamydia infection, such as indoleamine 2,3-dioxygenase 1 (IDO1), IDO2, MIG/CXCL9, IP-10/CXCL10 and I-TAC/CXCL11." (PMID 33799333, 2021). "The tryptophan-degrading activity of IDO1 was not induced significantly by Chlamydia infection alone, but the addition of IFNG greatly increased its activity." (PMID 34819931, 2021). "Western blot was used to determine whether Chlamydia infection and/or IFNG treatment induced IDO1 protein expression." (PMID 34819931, 2021). "Higher kynurenine/tryptophan ratio levels in women with an active Chlamydia infection supports the hypothesis of an anti-chlamydial IFN-γ immune response to the pathogen, subsequently, activating the enzyme IDO1 to deplete tryptophan into kynurenine." (PMID 29404279, 2018). "However, during Chlamydia infection in vitro, addition of IFNγ does not fully induce nuclear localization of its transcription factor STAT1 and expression of its target gene, IDO1." (PMID 39194253, 2024).
chronic lymphocytic leukemia (6 papers, 2020 to 2025). "Here, we investigated the functional role of the IDO1/Kyn/AHR axis in chronic lymphocytic leukemia (CLL)." (PMID 35371054, 2022). "The tryptophan-catabolizing enzyme IDO1 and its metabolite kynurenine were shown to be enhanced in patients with chronic lymphocytic leukemia (CLL), and their involvement in T cell suppression and immune escape was suggested." (PMID 33920868, 2021). "IDO1-expressing monocytic MDSCs were shown to accumulate in patients with chronic lymphocytic leukemia (CLL) and to suppress T cell activity and induce suppressive regulatory T cells (Tregs) in vitro." (PMID 33920868, 2021).
Cirrhosis (6 papers, 2015 to 2025). A chronic disorder of the liver in which liver tissue becomes scarred and is partially replaced by regenerative nodules and fibrotic tissue resulting in loss of liver function. "Previously, we observed that serum IDO1 level was decreased in patients with HBV-induced cirrhosis as compared to healthy volunteers, whereas serum IDO1 was dramatically increased in fibrotic mice induced by CCL414." (PMID 33414436, 2021). "We then found a positive correlation between the serum level of IDO1 and the degree of liver stiffness in the cirrhosis patients." (PMID 28465467, 2017). "A positive correlation between serum IDO1 levels and liver stiffness values was found in the cirrhosis patients." (PMID 28465467, 2017). "In the present study, we first discovered that the level of serum IDO1 was significantly decreased in patients with cirrhosis compared to HVs." (PMID 28465467, 2017). "Collectively, the results of this clinical study indicated that the serum IDO1 level was decreased in patients with HBV-induced cirrhosis compared with HVs." (PMID 28465467, 2017). "We first conducted clinical trials on patients with hepatitis B virus (HBV)-induced cirrhosis to investigate whether the serum level of IDO1 would change compared with healthy volunteers (HVs)." (PMID 28465467, 2017). "Interestingly, the serum level of IDO1 was decreased significantly in the patients with cirrhosis compared with the HVs." (PMID 28465467, 2017).
colorectal tumors (6 papers, 2012 to 2022). "IDO1 is highly expressed in colorectal tumors and is inversely associated with patient survival." (PMID 29685162, 2018). "IDO-1 has increased expression in multiple tumor cell types and is relatively highly expressed in colorectal tumors." (PMID 36612271, 2022). "Combination of photodynamic immunotherapy and IDO‐1 blockade efficiently eradicates CT26 colorectal tumors in the immunocompetent mice." (PMID 32328426, 2020). "A study on IDO1 expression in primary colorectal tumours demonstrated that higher IDO1 expression at the tumour invasion front correlates with progressive disease and impaired clinical outcome." (PMID 26359356, 2015). "Our study shows that IDO1 immunohistochemistry on pathological resection specimens of primary colorectal tumours can aid in making individualised therapeutic decisions." (PMID 22108515, 2012). "Reversing IDO1-mediated immunosuppression improved responses to immunogenic chemotherapy in a subcutaneous colorectal tumor model by promoting dendritic cell maturation, increasing tumor infiltrating T lymphocytes, and decreasing the numbers of regulatory T cells." (PMID 33536348, 2021).
cystic fibrosis (6 papers, 2012 to 2023). Autosomal recessive disorder caused by pathogenic variants in the CFTR gene (cystic fibrosis transmembrane conductance regulator), which encodes a chloride and bicarbonate channel expressed in epithelial cells, and follow the diagnosis criteria. "Similarly, Tα1 improved the inflammatory phenotype and promoted immune tolerance via IDO1 in a murine model of cystic fibrosis." (PMID 32817121, 2020). "In the present study, we performed genetic association studies in two different cohorts of susceptible patients [cystic fibrosis patients and recipients of hematopoietic stem cell transplantation (HSCT)], and identified IDO1 polymorphisms that associate with the risk of infection in both cohorts." (PMID 31134053, 2019). "In addition, the circadian regulation of IDO1 drives such diurnal changes in a pre-clinical model of cystic fibrosis, an autosomal recessive disease characterized by progressive lung function decline and recurrent infections, thus acquiring considerable clinical relevance." (PMID 36896128, 2023).
head and neck cancer (6 papers, 2017 to 2023). A primary or metastatic malignant neoplasm affecting the head and neck. "Among genes potentially responsible for OSCC-GB progression, upregulation of immune checkpoint genes—CD274, CD80, and IDO1—was also observed in head and neck cancer patients." (PMID 33980865, 2021). "Studies performed on head and neck cancer biopsies utilizing the spatial architecture of the tumor have identified markers such as PD-L1, PD-1, STING, IDO1, GZMB, and Ki67 to be differentially expressed between different locations of the tumor and being predictive of progressive disease." (PMID 38044986, 2023).
Hepatitis (6 papers, 2014 to 2024). Inflammation of the liver. "used combined blockade of PD‐1, CTLA‐4, and IDO1 to establish a mouse model of ICI‐induced hepatitis and studied the immune mechanism in this model." (PMID 39001676, 2024). "The patient with HLA-B27:04 had a pre-existing history of ankylosing spondylitis and developed grade 3 hepatitis on nivolumab with an IDO-1 inhibitor." (PMID 38668043, 2024). "In a previous study, IDO1 expression was enhanced in the liver of hepatitis model." (PMID 27598994, 2016).
Hypertension (6 papers, 2011 to 2025). The presence of chronic increased pressure in the systemic arterial system. "Considering that IDO1 inhibition facilitates a reversal in septic shock associated-hypotension and, moreover, diminishes the likelihood of fatality, Kyn constitutes a fruitful area of investigation regarding the creation of therapies for hypertension." (PMID 28377795, 2017).
leishmaniasis (6 papers, 2012 to 2025). Infectious disease that is transmitted through the bite of hematophagous female phlebotomine sand flies. "Tryptophan levels have been associated with leishmaniasis, by means of its regulation by the rate limiting enzyme indoleamine 2,3-dioxygenase (IDO-1)." (PMID 35384718, 2022). "Although the precise functions of IDO1 and PD1/PD-L1 in human leishmaniasis remain unclear, they are strongly associated with disease and treatment outcome." (PMID 40371647, 2025). "Although differing mechanisms of immunopathology may occur across the leishmaniasis disease spectrum, IDO1 and PD-L1 have been consistently identified in transcriptomics studies." (PMID 40371647, 2025). "In the context of leishmaniasis, the biological role and expression pattern of IL-24 is poorly studied, with one preprint report showing elevated levels of IL-24 in CD274+ and IDO1+ myeloid cells in human CL skin lesions." (PMID 39364404, 2024).
leprosy (6 papers, 2018 to 2025). Leprosy is a chronic infectious disease affecting primarily the skin and peripheral nervous system. "DEGs related to neurological and immunological terms identified IDO-1, mTOR signalling, TLR, T-cell, MAPK and Notch Pathways as important players in leprosy progression in susceptible hosts." (PMID 40788929, 2025). "We found that IDO1, a gene involved with tryptophan catabolism, is an excellent candidate for distinguishing leprosy lesions from other dermatoses." (PMID 34695167, 2021). "According to the latest data from single-cell analysis, IDO1 has been shown to be differentially expressed in Langerhans cells from leprosy lesions compared to healthy skin, corroborating our findings." (PMID 34695167, 2021). "Transforming growth factor beta, which is highly expressed in leprosy patients, is able to maintain high IDO-1 expression in DCs through phosphorylation of its immune-based inhibitory tyrosine motifs, leading to a sustained immunoregulatory effect." (PMID 29755459, 2018). "A recent transcriptomic analysis demonstrated that IDO1 expression could be used as a biomarker to discriminate skin lesions of leprosy patients from controls affected by other dermal conditions, such as granuloma annulare." (PMID 35281455, 2022). "The increase in pro-inflammatory mediators in COVID-19 and in leprosy may increase the activity of the enzyme Indoleamine 2,3-dioxygenase 1 (IDO1), which results in the production of kynurenine metabolites." (PMID 35281455, 2022). "Future studies should elucidate whether the increased IDO1 activity and increased levels of kynurenine metabolites in serum can be correlated with leprosy neuropathy in multibacillary patients." (PMID 35281455, 2022). "As for differentiating leprosy per se vs. ODD, genes IDO1, BLK (exon 11), CD38, CXCL11, and SLAMF7, all had an area under the curve (AUC) of at least 96% with their lower bound 97% confidence intervals above 90%." (PMID 34695167, 2021). "DCs are able to increase IDO1 expression and activity in response to IFN-γ, and IDO1 is highly activated in leprosy patients." (PMID 29755459, 2018). "IDO-1 was also described as required for successful infection of mice with L. major or Toxoplasma gondii, and enhanced expression of IDO-1 was highly discriminatory in lesions of leprosy patients." (PMID 35384718, 2022). "Indoleamine 2,3-dioxygenase 1 (IDO1) expression alone was highly discriminatory, followed by TLR10, BLK, CD38, and SLAMF7, whereas the HS3ST2 and CD40LG mRNA separated multi- and paucibacillary leprosy." (PMID 34695167, 2021). "When we directly compared LCs between a single leprosy biopsy and a single normal skin biopsy from which we performed bead-based LC enrichment (STAR Methods), we detected elevated expression of IDO1, STAT1, HCAR3, and MHC class I molecules (HLA-A, HLA-B, and HLA-F) in LCs in leprosy infection." (PMID 33053333, 2020).
liver disease (6 papers, 2017 to 2025). "The role of IDO-1 in liver diseases is not only related to the regulation of immune responses and fibrosis but also involves various physiological processes such as liver regeneration, oxidative stress, and inflammation." (PMID 39940736, 2025). "A complete understanding of the role of IDO1 in the modulation of cardiovascular and liver disease as a comorbidity warrants further investigations." (PMID 35563591, 2022). "A deeper understanding of kynurenine and its derivatives, as well as the rational design of IDO1 inhibitors in liver diseases, could provide new avenues for therapeutic intervention in liver diseases." (PMID 39940736, 2025). "It was confirmed that in different types of liver disease, the expression or activation of IDO1 changed, which could also affect the progression of disease through its regulation of immune responses." (PMID 28465467, 2017). "Compared to IDO-1, the role of TDO enzyme in liver disease remains understudied despite being the prominent KP enzyme under normal physiological conditions." (PMID 39774873, 2024). "With respect to hepatitis C virus (HCV)-infected liver disease, HCV infection stimulates IDO1 expression in hepatocytes." (PMID 28465467, 2017). "Using Apoe−/− and Apoe−/−Ido1−/− mice that were fed a high-fat and cholesterol-rich diet, we demonstrate an essential role of IDO1 in accelerating vascular but not liver disease in the same animals." (PMID 35563591, 2022).
Parkinson disease (6 papers, 2018 to 2024). A progressive degenerative disorder of the central nervous system characterized by loss of dopamine producing neurons in the substantia nigra and the presence of Lewy bodies in the substantia nigra and locus coeruleus. "We further show that carbidopa, an FDA-approved drug for Parkinson's disease as well as an AhR agonist, inhibits IDO1 expression in PDAC cells." (PMID 35997090, 2022). "Taken together, our study provides proof that targeting IDO1 in tumor cells can be a beneficial therapeutic approach for PDAC and expands the therapeutic applications of carbidopa beyond Parkinson's disease to target IDO1 in cancers." (PMID 35997090, 2022).
periodontitis (6 papers, 2012 to 2025). An acute or chronic inflammatory process that affects the tissues that surround and support the teeth. "Additionally, our data indicate that these cytokines trigger an immunosuppressive effect, at least partially, via IDO-1 expression in hPDLSCs, counteracting its destructive role during periodontitis." (PMID 33339125, 2020).